ST7 (suppression of tumorigenicity 7)
Description:
May act as a tumor suppressor.
Synonyms: FAM4A1; HELG; RAY1; TSG7; SEN4; ETS7q; FAM4A; NCRNA00026; ST7OT3; ST7-OT3
Tractability: Antibody: UniProt predicts a signal peptide or a membrane-spanning region. PROTAC: ubiquitination databases record sites on it; its protein half-life has been measured.
Gene: Protein-coding gene on chromosome 7 (116,952,980 to 117,230,812, forward strand). Ensembl gene ENSG00000004866.
Subcellular location: Membrane
Subcellular location (Human Protein Atlas): Nucleoplasm; Cytosol
Gene Ontology:
Molecular function: protein binding
Biological process: extracellular matrix organization; regulation of cell differentiation
Cellular component: nucleoplasm; membrane
Genetic constraint (gnomAD): Loss-of-function variants: 22 observed, 60.41 expected, observed/expected ratio (o/e) 0.36, 90% interval 0.26 to 0.52. The upper end of that interval is the gene's LOEUF score, 0.52, which puts it in group 2 of 6, group 1 being the genes least tolerant of losing a copy. Missense variants: 377 observed, 631.56 expected, observed/expected ratio (o/e) 0.6, 90% interval 0.55 to 0.65. Synonymous variants: 231 observed, 230.8 expected, observed/expected ratio (o/e) 1, 90% interval 0.9 to 1.12.
Homologues: Orthologues: rat ST7 (99% identical), chimpanzee ST7 (96% identical), pig ST7 (96% identical), mouse St7 (95% identical), dog ST7 (94% identical), tropical clawed frog st7 (92% identical), guinea pig ST7 (92% identical), macaque ST7 (91% identical), rabbit ST7 (85% identical), zebrafish st7 (74% identical), zebrafish st7 (69% identical), Drosophila melanogaster CG3634 (64% identical), and 1 more. Paralogues in human: ST7L (71% identical).
Diseases named in the same sentence as ST7 in open-access papers:
ST7 is named in the same sentence as 21 diseases in open-access papers, as found by Europe PMC text mining. Sharing a sentence is not in itself a finding about the gene and the disease. The quoted sentences say what the papers report.
colorectal cancer (3 papers, 2003 to 2021). A primary or metastatic malignant neoplasm that affects the colon or rectum. "ST7 is known to suppress the growth of multiple solid tumor types, including prostate, gastric, and colorectal cancer." (PMID 33793053, 2021). "In this study, we investigated the true frequency of ST7 gene mutations by examining 48 primary colorectal cancers, 48 primary gastric cancers that frequently show LOH on 7q31, and 48 primary hepatocellular carcinomas that show high-level expression of the ST7/RAY1 gene." (PMID 12799635, 2003). "Importantly, inhibition of CPCM components also caused a decrease of CRL4 E3 ligase activities and eventually led to an accumulation of ST7 (suppression of tumorigenicity 7), the specific substrate of CRL4 E3 ligases in colorectal cancer." (PMID 32140074, 2020).
autism (2 papers, 2019 to 2020). Persistent deficits in social interaction and communication and interaction as well as a markedly restricted repertoire of activity and interest as well as repetitive patterns of behavior. "The autism loci containing RAY1/ST7 (suppression of tumorigenicity 7) encode at least four non-coding genes (ST7OT1-4, ST7AS1-4) which are located in the sense or antisense chains that potentially regulate RAY1/ST7." (PMID 31824553, 2019). "It was also suggested that long noncoding RNA (lnc RNA) called ST7 overlapping transcript antisense 1-4 (ST7OT1-4), which possibly regulates the expression of RAY1/ST7, could be associated with autism." (PMID 32244359, 2020). "Genes that have long been mentioned as involved in the causation of autism are FOXP2, RAY1/ST7, IMMP2L, and RELN genes at 7q22-q33." (PMID 32244359, 2020). "Therefore, further studies have to be made to verify the function of RAY1/ST7 and its implications in autism." (PMID 32244359, 2020).
gastric cancer (2 papers, 2003 to 2021). A primary or metastatic malignant neoplasm involving the stomach. "ST7 mutations have been reported in breast, colon, esophagus, and gastric cancers." (PMID 33793053, 2021).
glioblastoma (2 papers, 2024). The most malignant astrocytic tumor (WHO grade IV). "The mRNA expression analysis also showed that the basal expression of both MET and ST7 are very low in the glioblastoma cases, in contrast to the very high basal expression of PTPRZ1." (PMID 38254850, 2024). "The ST7–MET fusion that couples the first exon of ST7 (suppressor of tumorigenicity 7) is a novel finding in glioblastoma, and has been described as an oncogenic event in non-small-cell lung carcinoma." (PMID 38254850, 2024). "Although these fusions are rare in glioblastoma, the incidence in the Combined cohort being 0.5% for ST7–MET and LMNA–NTRK1, 1.1% for PTPRZ1–MET and GOPC–ROS1, and 1.6% for FGFR3 fusions, they appear to be targetable alterations that also occur in other solid cancers." (PMID 38254850, 2024). "The fourth largest subgroup, G6/Multi-RTK, was detailed by describing a novel gene fusion ST7–MET, rare PTPRZ1–MET, LMNA–NTRK1 and GOPC–ROS1 fusions and their overexpression mechanisms in glioblastoma." (PMID 38254850, 2024).
hepatocellular carcinoma (2 papers, 2003 to 2016). A malignant tumor that arises from hepatocytes. "We conclude that mutations in the ST7 gene are rare in primary colorectal, gastric, and hepatocellular carcinomas." (PMID 12799635, 2003). "We conclude that ST7 gene mutations are rare in colorectal, gastric, and hepatocellular carcinomas." (PMID 12799635, 2003). "To ascertain the frequency of mutations of the ST7 gene in cancer cells, we examined mutations in the ST7 coding sequence in 48 colorectal, 48 gastric, and 48 hepatocellular carcinomas using polymerase chain reaction–single-strand conformational polymorphism and direct sequencing." (PMID 12799635, 2003).
mantle cell lymphoma (2 papers, 2011 to 2021). Mantle cell lymphoma is a rare form of malignant non-Hodgkin lymphoma affecting B lymphocytes in the lymph nodes in a region called the ``mantle zone''. "By contrast, the ST7 gene is a tumour suppressor gene that is underexpressed in mantle cell lymphoma." (PMID 21957467, 2011).
Blastocystis infection (1 paper, 2023). "As the murine model is not exactly reflective of the human gut in the case of Blastocystis infection, it is necessary to perform, in future studies, human gut microbiome studies to reveal the precise roles of ST4 and ST7 on intestinal inflammation." (PMID 36793854, 2023).
breast tumours (1 paper, 2011). "ST7 has been reported as a tumour-suppressor gene involved in a variety of other human cancers and cell lines derived from breast tumours have been shown to harbor mutations in ST7." (PMID 22188678, 2011).
esophageal adenocarcinoma (1 paper, 2023). A malignant tumor with glandular differentiation arising predominantly from Barrett mucosa in the lower third of the esophagus. "ST7-eQTL rs4730777 colocalizes with esophageal adenocarcinoma GWAS SNP (rs2188554), suggesting that regulation of ST7 in adipose tissue may be involved in other cancer types." (PMID 37543566, 2023).
pancreatic cancer (1 paper, 2021). "We found a reverse association between MIB1 and ST7 protein levels in pancreatic cancer tissues (Pearson correlation r = −0.3535, P = 0.0372)." (PMID 33793053, 2021). "To assess the importance of ST7 in the tumor‐promoting effects of MIB1 in pancreatic cancer, we used BxPC‐3 cells expressing shControl, shMIB1, shST7, and shMIB1/shST7." (PMID 33793053, 2021). "Here, we found that the ST7/IQGAP1 axis plays an essential role in pancreatic cancer progression; nevertheless, the mechanism of how ST7 inhibits IQGAP1 requires further investigation." (PMID 33793053, 2021). "Together, these data indicate that MIB1 promotes ST7 polyubiquitination and proteasomal degradation in pancreatic cancer." (PMID 33793053, 2021). "In particular, we identified that IQGAP1, a well‐known cytoskeleton regulator, was downregulated by ST7 in pancreatic cancer." (PMID 33793053, 2021). "Consistently, our RNA‐seq analysis indicated that ST7 regulated the expression of actin cytoskeleton‐related genes in pancreatic cancer." (PMID 33793053, 2021). "In this study, we show that MIB1 overexpression drives pancreatic cancer progression by targeting ST7 for proteasomal degradation." (PMID 33793053, 2021). "Conversely, MIB1 overexpression decreased ST7 protein levels in pancreatic cancer cell lines, although ST7 mRNA levels remained unchanged." (PMID 33793053, 2021). "Our data suggest that MIB1 overexpression drives pancreatic cancer progression by targeting ST7 for degradation." (PMID 33793053, 2021). "Although ST7 has been reported to suppress tumor growth in multiple cancer entities, its role in pancreatic cancer remains unknown." (PMID 33793053, 2021). "Although the c‐Myc‐dependent CRL4DCAF4 E3 ligase has been shown to mediate ST7 degradation in colitis‐associated cancer, the post‐translational modifications of ST7 in pancreatic cancer remain unknown." (PMID 33793053, 2021). "In conclusion, our research shows that the MIB1/ST7/IQGAP1 axis is essential for pancreatic cancer progression, and MIB1 inhibition may serve as a novel therapeutic strategy in patients with pancreatic cancer." (PMID 33793053, 2021). "We also report that in pancreatic cancer, ST7 suppresses MIB1 expression." (PMID 33793053, 2021). "Furthermore, we identified ST7 as a critical factor suppressing tumor development and progression in pancreatic cancer by negatively regulating IQGAP1 expression." (PMID 33793053, 2021). "Our research shows that the MIB1/ST7/IQGAP1 axis is essential for pancreatic cancer progression, and MIB1 inhibition may serve as a novel therapeutic strategy in patients with pancreatic cancer." (PMID 33793053, 2021). "Similarly, ST7 knockdown enhanced pancreatic cancer cell invasion in vitro." (PMID 33793053, 2021). "Finally, we show that the MIB1/ST7 axis modulates IQGAP1 expression in pancreatic cancer." (PMID 33793053, 2021). "Therefore, the MIB1/ST7/IQGAP1 signaling axis is an important mediator of pancreatic cancer progression, and inhibiting MIB1 may prolong the survival of patients with pancreatic tumors." (PMID 33793053, 2021). "Importantly, we identified ST7 as a novel substrate of MIB1 in pancreatic cancer." (PMID 33793053, 2021). "Overall, these data indicate that MIB1 targets ST7 for degradation, thereby increasing IQGAP1 expression levels and promoting pancreatic cancer progression." (PMID 33793053, 2021). "The ability of ST7 silencing to increase pancreatic cancer cell growth was attenuated by the combined silencing of IQGAP1 and ST7." (PMID 33793053, 2021). "We also evaluated the protein levels of ST7 and MIB1 in a pancreatic cancer tissue microarray (n = 35 samples)." (PMID 33793053, 2021). "In the present study, we identified that by inducing ST7 degradation, MIB1 upregulates IQGAP1 and enhances pancreatic cancer progression." (PMID 33793053, 2021).
pancreatic cancer (continued). "To get further insight into the antitumor effects of ST7 in pancreatic cancer, we performed RNA‐seq analysis in BxPC‐3 cells with or without ST7 silencing." (PMID 33793053, 2021). "Importantly, ST7 silencing significantly upregulated IQGAP1, which has been shown to promote pancreatic cancer proliferation." (PMID 33793053, 2021). "Furthermore, we identified ST7 as a critical factor suppressing tumor development and progression by negatively regulating IQGAP1 expression in pancreatic cancer." (PMID 33793053, 2021).
pancreatic tumors (1 paper, 2021). "Furthermore, we found that ST7 suppressed tumor growth by downregulating IQ motif containing GTPase activating protein 1 (IQGAP1) in pancreatic tumor cells." (PMID 33793053, 2021).
prostate carcinoma (1 paper, 2021). A carcinoma that arises from epithelial cells of the prostate gland. "Additionally, ST7 overexpression has been shown to suppress the in vivo tumorigenicity PC‐3 prostate cancer cells, suggesting that ST7 has tumor suppressor functions." (PMID 33793053, 2021).
tumor (16 papers, 2002 to 2025). "On the one hand, inhibiting PRMT5 activity can promote cell cycle arrest and the apoptosis of tumor cells, reducing its metastatic capability; on the other hand, it can restore the expression of tumor suppressor genes such as ST7 and PTEN in gliomas." (PMID 40450009, 2025). "Previously studies have shown that ST7 suppressed tumor growth by modulating the expression of genes involved in cellular structure and architecture." (PMID 33793053, 2021). "The decreased activities CRL4DCAF4 E3 ligases resulted in repression of ST7 ubiquitination, leading to its accumulation, which inhibited tumor cell growth in vitro and in vivo." (PMID 32140073, 2020). "The degraded ST7 lost its role in preventing tumor cell growth and resulted in the occurrence of CRC." (PMID 32140074, 2020). "We also evaluated the effects of knockdown and inhibition of CPCM components on CUL4A/4B expression, ST7 ubiquitination, oncogenic phenotypes, and in vivo tumor growth." (PMID 32140074, 2020). "ST7 was demonstrated to function as tumor suppressor in PCa by remodeling tumor microenvironment." (PMID 37008945, 2023). "The accumulated ST7 functioned as a tumor suppressor to inhibit tumor growth." (PMID 32140074, 2020). "The accumulated ST7 functioned as a tumor suppressor to inhibit the growth of cancer cells." (PMID 32140073, 2020). "It was interesting that two tumor suppressive genes, Cav1 and ST7, surrounded the Met locus." (PMID 22952676, 2012). "ST7 is a candidate tumour suppressor gene at human chromosome locus 7q31.1." (PMID 12107844, 2002). "Therefore, the ST7 gene represents a novel candidate gene for the tumour suppressor at this locus." (PMID 12799635, 2003). "In addition, S-phase kinase-associated protein 2 (Skp2) specifically degrades cyclin-dependent kinase inhibitor 1B (CDKN1B), and mindbomb homolog 1 (MIB1) enhances the ubiquitin-mediated degradation of suppression of tumorigenicity 7 (ST7); both Skp2 and MIB1 promote tumor proliferation." (PMID 38174069, 2023). "Although ST7 and CAV1 have been reported to be candidate tumor suppressor in several types of cancer, no direct evidences support their relationship with gastric carcinogenesis." (PMID 20626849, 2010).
cancer (10 papers, 2003 to 2024). A tumor composed of atypical neoplastic, often pleomorphic cells that invade other tissues. "St7 has been reported to be a tumor suppressor gene involved in multiple types of cancer." (PMID 19133160, 2009). "However, more recent studies have reported that ST7 mutations are infrequent or absent in primary cancer and cell lines." (PMID 12799635, 2003). "Similar to the ST7 tumor suppressor gene, ST7L can inhibit the proliferation, migration, and invasion of cancer cells." (PMID 36003381, 2022). "Since there have been no reports on the expression of the ST7 gene in cancer cells, further studies are needed to understand the role of this gene in carcinogenesis and the progression of these cancers." (PMID 12799635, 2003).
ST7 also shares sentences with these, for which no sentence is quoted: chronic lymphocytic leukemia (1 paper); Crohn disease (1); glioma (1); infection (1); non-small cell lung carcinoma (1); schizophrenia (1); viral infection (1).